STAT3 (signal transducer and activator of transcription 3)
Diseases named in the same sentence as STAT3 in open-access papers (continued):
Sharing a sentence is not in itself a finding about the gene and the disease.
tumor (continued). "miR-124 targets many proteins like SCP1, Rho-associated protein kinase 1 (ROCK1), STAT3, matrix metallopeptidase 9 (MMP9), and inhibits tumor cell proliferation in GBM." (PMID 37508353, 2023). "We observed a direct correlation between LIF concentration and STAT3 activation, indicating that, in these tumor-derived cells, it is mainly LIF or a LIF-induced secreted factor that activates STAT3." (PMID 38137514, 2023). "In most human cancers, JAK/STAT3 signaling is involved in CSC stemness maintenance and CSC-associated tumor metastasis." (PMID 37853437, 2023). "Intriguingly, the systemic administration of STAT3/EKEVs significantly suppressed subcutaneous PC9-GR4-AZD1 tumor xenografts in nude mice by STAT3 mediated apoptosis." (PMID 36740689, 2023). "The signal transducer and activator (STAT3) is known to play a key role in the regulation of tumor response." (PMID 37109658, 2023). "By activating signal transducer and activator of transcription 3 (STAT3), which is an important transcription factor in tumor-associated inflammation, FAP has been shown to mediate the inflammatory effects of CAFs." (PMID 38313431, 2023). "This conclusion also provided evidence that TMTC3 facilitated tumor angiogenesis through STAT3 signaling pathway in ESCC." (PMID 37752569, 2023). "In an in vivo study, gallic acid reduced Src-mediated phosphorylation of STAT3, thereby promoting cell cycle arrest and apoptosis in a mouse xenograft tumor model." (PMID 37568796, 2023). "Our results reveal that adenosine‐A2B signalling in Olaparib‐resistant cells induces IL‐6 secretion and subsequent STAT3 activation, which promotes tumour cell growth." (PMID 37278400, 2023). "Inhibition of STAT3 signaling has been shown to inhibit tumor growth and improve survival; therefore, it is a molecular target for cancer treatment." (PMID 37653036, 2023). "The STAT3 signaling pathway, including the phosphorylation levels of STAT3 and the downstream protein expression, is directly related to tumor proliferation." (PMID 38067413, 2023). "Recent reports have shown that the inhibition of the STAT3 signaling pathway in drug-resistant cells can restore the chemotherapy effect, as tumor cells become resistant to platinum chemotherapy drugs by activating the STAT3 signaling pathway." (PMID 38031104, 2023). "These TIL-B then secrete lymphotoxin, which activates NF-κB signaling and STAT3 in the cancer cells, resulting in androgen-refractory growth and tumor progression." (PMID 37046842, 2023). "Resveratrol (Res) inhibits tumor growth and improves drug chemosensitivity by targeting STAT3 signaling." (PMID 37298405, 2023). "G7 mAb displayed an anti-tumor effect when coupled with cetuximab, perhaps by disrupting STAT3 signaling." (PMID 37846296, 2023). "STAT3 signaling has been shown to have central role in CSCs in promoting cell proliferation, survival, tumor invasion, angiogenesis, and immunosuppression." (PMID 37853413, 2023). "STAT3 is activated in tumor cells and different immune cells in the GBM microenvironment, leading to severe immunosuppression." (PMID 36923251, 2023). "Compared with KRASWT tumors, the tumor samples with KRAS mutations displayed higher expression of CD47 and p-STAT3." (PMID 36413402, 2023). "The mechanistic pathway of valeric acid is involved with downregulation of Signal transducer and activator of transcription-3 (STAT3)/cyclin D1 pathway which is directly related to tumour cell proliferation." (PMID 38112935, 2023). "As a natural active ingredient, anthocyanin can block the proliferation of various tumor cells through the terminal differentiation of tumor cells, and further induce the apoptosis of tumor cells through the STAT3 and NF-κB signaling pathways regulated by ROS." (PMID 36677726, 2023).
tumor (continued). "In conclusion, IL-25 can bind to the receptor and activate multiple downstream signaling pathways, including NF-κB, MAPK, JAK and STAT3, which play diverse roles in self-renewal, survival and apoptosis of cells as well as inflammation, tumor progression." (PMID 37005677, 2023). "In the meanwhile, we observed that the level of KDF1, AKT, p-AKT and p-STAT3 and the ratio of Ki-67-positive cells were significantly increased in the tumor tissues derived from KDF1-overexpressing cells." (PMID 38137415, 2023). "Multiple cell types in the tumor microenvironment produce IL-6, leading to activation of JAK/STAT3 signaling in both tumor and tumor-infiltrating immune cells." (PMID 37686695, 2023). "A STAT3 inhibitor, napabucasin, has been shown to exhibit synergism with paclitaxel in promoting tumor regression and patient survival in extensively pretreated NSCLC." (PMID 37568796, 2023). "-Promotes EMT of HCC tumour cells via JAK2/STAT3/Snail signalling pathway and hence induces their migration and invasion." (PMID 37894344, 2023). "The results of p-STAT3 immunohistochemical staining of the tumor tissue sections showed that the expression of p-STAT3 was significantly reduced in the tumor tissues of the TSN group, compared with that in the NS and 5-FU groups." (PMID 37946196, 2023). "The downstream pathway of STAT3 activated by IL-6 is also believed to be closely related to the proliferation, metastasis, and drug resistance of tumor." (PMID 37404767, 2023). "CAAs increase the secretion of IL-6 and leptin, which activate the JAK/STAT3 axis in BC cells and reduce the sensitivity of tumor cells to the toxic effects of NKs." (PMID 36765683, 2023). "In tumor tissue from BC patients, NF-kB, STAT3 and their target genes (i.e., cyclin-D1, VEGF-A, and TGFβ1) have been found to be activated in comparison to healthy tissue, suggesting that chronic inflammation can promote tumor development." (PMID 36614308, 2023). "In most cancers, STAT3 is overactivated and promotes tumor progression by regulating various biological processes, such as proliferation, apoptosis, angiogenesis, and immune response, which are generally associated with poor clinical prognosis [10,14−17]." (PMID 37724127, 2023). "In another study, MM-derived EVs were reported to modulate the STAT3 pathway in endothelial cells, not only promoting angiogenesis but also inducing tumor growth via the release of VEGF and IL-6, respectively." (PMID 37371477, 2023). "Sustained activation of STAT3 promotes the growth, survival and metastasis of cancer cells, and inhibits the anti-tumor immune response." (PMID 36986673, 2023). "To better uncover the mechanism of IL-6/STAT3 signaling in TAM-educated tumor cells, we performed RNA-seq on MCF-7 cells after coculturing with TAMEV−Exo or TAMOE−Exo." (PMID 36797769, 2023). "miR-1246 transfection in ECs increased the expression of adhesion molecule ICAM-1 via activation of STAT3, followed by increased tumor cell adhesion to ECs." (PMID 37124539, 2023). "Odateet al. showed that STAT3 inhibition decreased the tumor-initiating potential of NB cells and increased sensitivity to cisplatin." (PMID 36916296, 2023). "Studies have shown that the tumor inflammatory microenvironment can continuously activate STAT3-related signaling pathways." (PMID 36814560, 2023). "They transfer onco-miRs as for example miR155, miR214, miR21 or tumorigenic transcription factors (such as Stat3) into tissue-resident microglia, infiltrating myeloid-derived macrophages and tumor-infiltrating regulatory T cells." (PMID 38293652, 2023).
tumor (continued). "Myristone induces apoptosis in two types of cancer cells (HeLa and PC3) by activating caspase and downregulating NF-KB and STAT3 signaling cascade inhibits tumor cell proliferation." (PMID 37799727, 2023). "Of note, we identified that a STAT3 inhibitor augments the efficacy of standard chemotherapy and inhibits MB tumor growth in an intracranial orthotopic mouse model." (PMID 37190167, 2023). "These events promote the activation of JAK/STAT3 signaling through integrin α2β1, which triggers sustained tumor growth and cancer recurrence." (PMID 37441462, 2023). "Mechanistically, we also show that tumor cells are able to induce miR-214 production in stroma cells, following the activation of IL-6/STAT3 signaling, which is then released via EVs subsequently up-taken by cancer cells." (PMID 36639824, 2023). "Inhibiting the activation of STAT3 using knockout systems or inhibitors can significantly repress tumor progression, emphasizing the importance of blocking the STAT3 signal cascade in cancer therapy." (PMID 38031104, 2023). "Persistent STAT3 activation in the presence of HSP90 is a possible intracellular consequence of HSP delivery to the muscle cell by tumor derived exosomes." (PMID 36672227, 2023). "The Romana Mikyskova groups demonstrate that Stattic and its analogues inhibit the STAT3 phosphorylation in senescent tumor cells." (PMID 37821959, 2023). "In the tumor tissues, STAT3 phosphorylation was strengthened, and HIF-1A expression was distinctly upregulated in the TRIM14 overexpression group compared to the vector group (p < 0.05)." (PMID 37628777, 2023). "In patient-derived primary tumor tissues, the expression of STAT3 and IL-1β displayed a positive correlation." (PMID 36922898, 2023). "This interaction ultimately results in the inactivation of the IL-6/STAT3 signaling pathway, thereby contributing to the tumor-suppressive effects of TSLNC8 in HCC." (PMID 37781073, 2023). "This resulted in a STAT3‐mediated anti‐angiogenic phenotype and a reduction in tumour growth in vivo." (PMID 35303381, 2023). "For example, SERPINA1 showed close connections to CD8A in CD8+ T cells, CD68 in tumor-associated macrophages, IRF6 in M1 macrophages, NRP1 in DCs, STAT3 and IL17A in Th17 in most digestive cancers." (PMID 37511325, 2023). "OLT1177 disrupts IL-1β/IL-6/STAT3 axis in TME resulting in reduced tumor growth through attenuating immunosuppressive activities in MDSCs, and the anti-tumor effect is further enhanced in combination with anti-PD-1." (PMID 36932407, 2023). "The activation of STAT3 in the tumor-infiltrating Treg cells is significantly higher compared to Treg cells of normal cellular origin in the spleen." (PMID 36923251, 2023). "It has been shown that STAT3 inhibition in tumor cells decreases the expression of E6 and E7 proteins." (PMID 37372319, 2023). "The NF-κB and signal transducer and activator of transcription 3 (STAT3) inflammatory pathways are major pathways that drive pro-tumor activities of TAMs." (PMID 36922898, 2023). "These HSPs are packaged into exosomes where they influence the tumor microenvironment, inhibit immune reactions to tumor cells, and initiate pro-cachectic STAT3 activation in skeletal muscle." (PMID 36672227, 2023). "Aberrantly activated STAT3 occurs frequently in multiple cancer types; plays an important role in tumor formation, metastasis, and drug resistance; and is associated with poor clinical prognosis of cancer." (PMID 37240202, 2023). "Previous research has suggested that apigenin can suppress tumor growth in various cancers by targeting the STAT3 signaling pathway." (PMID 37970406, 2023). "The signal transducer and activator of transcription 3 (STAT3) is often activated in SCLC; this is partly attributed to tumor-associated macrophages (TAMs)." (PMID 38203275, 2023).
tumor (continued). "In inflammation and tumors, IL‐6‐mediated STAT3 can also participate in the autonomous migration of cells by regulating growth factors, forming an inflammation cascade amplification effect and tumor metastasis." (PMID 37382258, 2023). "The signal transducer and activator of transcription 3 (STAT3) act as a marker of tumor angiogenesis, interacting with Src and forming a complex with paxillin." (PMID 37175948, 2023). "This pathway of inhibition suggests that indirubin can inhibit angiogenesis of the tumor by suppressing the JAK2/STAT3 pathway." (PMID 37173951, 2023). "Results were recapitulated only with the use of the JAK-specific inhibitor AG490, indicating that resveratrol anti-tumor activity was likely related largely to the inhibition of STAT3 signaling." (PMID 37173951, 2023). "JAK2/STAT3 signaling pathway plays a key role in cell proliferation, division, migration, tumor formation and immune cell maintenance." (PMID 37465679, 2023). "Vascular endothelial growth factor (VEGF) enhances the sensitivity of tumor vessels to VV infection, depresses the antiviral response by Erk1/2 and Stat3 signaling and upregulates the expression of PRD1-BF1/Blimp1 in the tumor vasculature." (PMID 38169820, 2023). "Aberrant STAT3 activation triggers tumor progression through oncogenic gene expression in numerous cancer types including malignant gliomas." (PMID 37190507, 2023). "Direct interaction of CD40 on MDA-MB231 cells with CD40L on T-cells was shown to upregulate Transforming Growth Factor-beta (TGF-β), induce Th17 differentiation, and increase the proliferation of tumor cells via STAT-3 signaling." (PMID 37835465, 2023). "STAT3 is transcriptionally hyperactive in numerous tumor cells and serves as an immune checkpoint in immune-associated tumor cells." (PMID 36985125, 2023). "Aberrant constitutive activation by STAT3 phosphorylation occurs in a number of human tumours and promotes tumour progression, including promotion of metastasis." (PMID 36825563, 2023). "HMGB1 upregulation and the successive overexpression of IL-23, IL-17 and IL-6, followed by STAT3 activation, promotes tumor growth." (PMID 37772080, 2023). "With decreased HIF-1 and reduced STAT3 activity in the hypoxic tumor microenvironment (TME), M-MDSCs acquire the phenotype of tumor-associated macrophages (TAMs)." (PMID 36978204, 2023). "p38, STAT3, ERK1/2, and JNK phosphorylation were generally higher in ATF4-deficient tumours, which expressed more EREG but less FGF21 mRNA." (PMID 36996941, 2023). "In a recent study, it was demonstrated that FTY720, by suppressing the S1PR1/STAT3 loop, inhibited tumor growth and desmoplasia and suppressed resistance to the chemotherapy drug gemcitabine." (PMID 36714534, 2023). "TGF-β-stimulated CAFs activate STAT3 signaling in cancer cells, mediating tumor metastasis through the secretion of IL-11." (PMID 36600243, 2023). "JAK/STAT3 pathway activation is upregulated in SHH MB tumor cells following treatment with selumetinib." (PMID 37726268, 2023). "Second, to reinforce the potential of applying MHME to TNBC’s chemotherapy regimens, murine models of TNBC must be employed to validate tumor growth retardation and p-STAT3 downregulation in tumor-planted mice under MHME administration." (PMID 37893115, 2023). "It is worth mentioning that S1PR1 plays an indispensable role in maintaining persistent activation of STAT3 by regulating tumor cells and tumor-infiltrating myeloid cells in primary tumors." (PMID 36714534, 2023). "In this study, anti-PD1 antibodies led to a decrease in the number of tumor cells and enhanced tumor apoptosis by blocking the p-STAT3/p-Erk1/2 signaling pathway." (PMID 37958467, 2023). "Together, our work reveals a new role for ROR1/STAT3 signaling in tumor heterogeneity and inflammation in OC." (PMID 37400436, 2023). "The STAT3 inhibitor inhibited tumor growth by approximately 50% in M-WT mice and by approximately 30% in M-KO mice." (PMID 37308559, 2023).
tumor (continued). "STAT3 triggers cellular transformation and facilitates tumor initiation and progression by regulation of c-Myc, Bcl-xL, CCND1, and VEGF." (PMID 36740668, 2023). "During cancer progression, JAK/STAT3 signaling enhances tumor proliferation, survival, invasion, immune evasion, and metastasis." (PMID 37190141, 2023). "Subsequently, we compared the different phosphorylation features of STAT3 in normal and tumor tissues using the CPTAC dataset." (PMID 36977736, 2023). "Given the self-renewal potential of CSCs to generate diverse cancer cells and tumor heterogeneity, inhibiting STAT3 can be an attractive strategy in tumor therapy." (PMID 38017510, 2023). "This XIST-driven production of IL-6 from ALDH− bulk tumor cells preferentially binds to IL6R on ALDH+ CSCs to drive STAT3 activation and expression of key CSC factors (i.e., c-MYC, KLF4 and SOX9), promoting self-renewal of ALDH+ CSCs." (PMID 36922677, 2023). "STAT3 transcriptional activity can trigger a metabolic switch to aerobic glycolysis to regulate mitochondrial activity, a prominent metabolic feature of tumor cells." (PMID 37573301, 2023). "STAT3 involved in tumor immunity and inflammation through contributing to pro-oncogenic inflammatory pathways, such as IL-6-GP130-JAK and NF-kappaB pathways." (PMID 37853057, 2023). "Herein we aimed to reveal a novel function of IL-11 through STAT3 signaling in regulating tumor immune evasion." (PMID 37365574, 2023). "STAT3 inhibition facilitated the phagocytosis of tumor infiltrated DCs and macrophages (PMID:35665592)." (PMID 37552127, 2023). "AL has been reported to have effective activity in reducing tumor angiogenesis and growth, by preventing STAT3 activation in CRC cells in in vivo and in vitro experimental treatments." (PMID 37242800, 2023). "CCL2 is a major player in proliferation, migration, invasion, and tumor growth, via phosphorylation of NF-κB and STAT3 pathways." (PMID 38170015, 2023). "Gene set enrichment analysis (GSEA) of bulk RNA sequencing showed high stromal STAT3 tumours were characterised by enrichment of IFNγ, upregulation of KRAS signalling and inflammatory signalling Hallmark pathways." (PMID 37199043, 2023). "STAT3 pathway in senescent tumors establishes a SASP-dependent microenvironment that contributes to tumor progression and therapy resistance." (PMID 37752122, 2023). "Th17 cells release IL-17, which promotes STAT3 phosphorylation in tumour cells, thereby promoting tumour development." (PMID 38032415, 2023). "Collectively, these data indicate that TCAF2‐induced Wnt5a secretion through inhibiting TRPM8 in TPCs, which activates the STAT3 signaling pathway in tumor cells, thus facilitating CRCLM." (PMID 37635201, 2023). "The team of Zaki found that NF-κB, ERK, and STAT3 signaling pathways were highly activated and that tumor incidence was increased in the colon of Nlrp12-/- mice." (PMID 37020871, 2023). "TAMs can also activate the NF-κB/STAT3/ERK pathway within tumor cells through the release of pro-inflammatory cytokines, such as TNF-α and IL-6." (PMID 38001753, 2023). "It further blocks STAT3 dimerization and transcriptional activity after entering the nucleus, thus inhibiting the proliferation of tumor cells." (PMID 38071213, 2023). "Previous studies have shown that IL-20 subfamily members exert an effect by activating STAT3 (Tyr705) signaling pathway, which plays a crucial role in tumor progression." (PMID 38098005, 2023). "We found that Lan C induced a significant increase in caspase-9 and caspase-3 activity and a significant decrease in STAT3 expression in tumor tissues, consistent with the results in vitro experiments." (PMID 37397486, 2023). "Mechanistically, TRIM29 downregulation suppresses the expression of the tumor suppressor ZNF750 by activating the STAT3 signaling pathway." (PMID 37365152, 2023).